EZH2 (enhancer of zeste 2 polycomb repressive complex 2 subunit)
Diseases named in the same sentence as EZH2 in open-access papers (continued):
Sharing a sentence is not in itself a finding about the gene and the disease.
tumor (continued). "Therefore, it has been hypothesized that EZH2 inhibitors, which are currently part of clinical studies, can overcome resistance to ICB by targeting tumor cells and modulating the tumor microenvironment." (PMID 32041674, 2020). "EZH2 is a catalytic component of the polycomb repressive complex 2 (PRC2), which uses its HMT activity to catalyze the trimethylation of lysine at position 27 of histone H3, resulting in the suppression of downstream tumor suppressor genes such as E-cadherin, P16 INK4α, P57, and PSP94." (PMID 32859239, 2020). "Thus, both EZH2 expression and EMT contribute to tumor malignancy and metastatic activity." (PMID 31042721, 2019). "To verify whether dysfunctional T cells are enriched in tumor-specificities at this early time point, we took advantage of MHC dextramers to identify tumor-specific (WT1, PRAME, or EZH2) and control viral-specific (cytomegalovirus-CMV) CD8+ T cells from patients." (PMID 30911002, 2019). "However, transgenic expression of wild-type EZH2 in mammary and prostate glands does not lead to tumor development." (PMID 31704972, 2019). "Enhancer of zeste homolog 2 (EZH2), a methyltransferase and the core catalytic element of the polycomb-repressive complex 2 (PRC2), can induce genome-wide histone H3 lysine 27 trimethylation (H3K27me3) and acts as an oncogene by repressing tumor suppressor genes in cancers." (PMID 31171769, 2019). "Similarly, we find that oncogenic insults change the set of genes repressed by EZH2, with a critical switch induced by activation of oncogenic RAS signalling that leads to de‐repression of tumour‐promoting transcription factors and de novo silencing of tumour‐suppressive ones." (PMID 31468686, 2019). "It is not known whether EZH2 phosphorylation can be mediated by upstream MELK and whether the process underlying phosphorylation is indispensable for tumor progression." (PMID 31380279, 2019). "Furthermore, the interaction between MELK/EZH2 complex and NF-κB preferentially occurs in GSCs compared with non-stem-like tumor cells." (PMID 31380279, 2019). "However, in the multivariate analysis, which controlled the effect of tumour lymph node staging, the expression levels of EZH2 no longer predicted the prognosis of patients." (PMID 30542123, 2018). "Interestingly, tumor progression and poor clinical outcome have also been observed upon EZH2 overexpression in the tumor vasculature rather than in the cancerous cells." (PMID 30103412, 2018). "Consistently, by facilitating binding of EZH2 to its target loci, MALAT1 drives H3K27 trimethylation and repression of tumor suppressor genes or microRNAs, leading to epithelial to mesenchymal transition, migration/invastion, cell proliferation, and escape from apoptosis in several tumor types." (PMID 29739426, 2018). "Likewise, inhibition of EZH2 with the investigational drug tazemetostat (EPZ-6438) resulted in potent cell killing of MRT cells in culture, significant tumour growth inhibition in mouse xenograft models of MRT and objective responses among MRT patients in a phase 1 clinical trial of the drug." (PMID 29685962, 2018). "In addition, EZH2-mediated H3K27me3 is able to induce silencing of the IL-15R, CD122, and NKG2D receptor proteins, hence suppressing NK cell expansion and decreasing the cytotoxic targeting of tumor cells." (PMID 30558227, 2018). "Although several previous studies have proposed that EZH2 may be a potential marker for bladder cancer, the results regarding the relationship between EZH2 expression and tumour prognosis are inconclusive, and no consensus has been reached." (PMID 30542123, 2018). "Of note, tumours lacking Ezh2 did not have altered expression of other Forkhead box family members." (PMID 29959321, 2018).
tumor (continued). "Enhancer of zeste homolog 2 (EZH2), the catalytic subunit of the polycomb repressive complex 2 (PRC2), regulates the expression of thousands of genes to control developmental programs, maintain proliferative capacity and repress tumor suppressors in many forms of cancer." (PMID 29774113, 2018). "Furthermore, research in the mechanism found PVT1 could target genes such as LASP1, FOXM1, RSPO1, p15, p16, EZH2, TSHR, and NOP2 to promote tumor cell proliferation, migration and invasive capability in vitro." (PMID 29088881, 2017). "Whereas KRAS tumour organoids were significantly decreased when passaged in continued 5 μM GSK126, organoids grown in the presence of tamoxifen (and therefore Lkb1 null) were equally passaged in continued presence of the EZH2 inhibitor (P=0.0113 for Kras, P=0.132 for KRAS/Lkb1)." (PMID 28387316, 2017). "Both downregulation of EZH2 by si/shRNA or pharmacological inhibition of EZH2 in the S462 (NF1-derived MPNST) and MPNST724 (spontaneous MPNST) cell lines severely affected cellular proliferation rates, induced apoptosis and interfered with tumor formation in an MPNST724 xenograft model." (PMID 28813519, 2017). "Thus, we have demonstrated that EZH2 and BET proteins activity were required for the growth of PDGFB/H3K27M NSCs, inhibition of these two group of proteins showed an impressive interfere in tumor progression." (PMID 29118968, 2017). "Further, although Ezh2 deficiency did not affect the capacity of Pmel-1 cells to produce IFN-γ during the effector phase (7 days), it caused a reduction of IFN-γ-producing cells by 35 days, suggesting an impaired persistence of tumor-reactive T cells." (PMID 29242551, 2017). "Also, β-catenin protein was localized to nucleus in xenograft tissues formed by EZH2-overexpressing HeLa cells and to membranes or no staining in other tumor tissues formed by EZH2-depleted HeLa and SiHa cells and control cells by immunohistochemical staining." (PMID 27092879, 2016). "EZH2 was highly expressed in CCSKs irrespective of whether the tumour harboured the BCOR-ITD or the YWHAE-NUTM2B/E fusion transcript (not shown)." (PMID 26848979, 2016). "Interestingly, alternative epigenetic silencing mechanisms exist, like the overexpression of EZH2, a key member of the Repressive Polycomb Complex, PRC2, that in addition to silence many genes, including tumour suppressor genes, can also silence different microRNAs in cancer cells." (PMID 26983574, 2016). "Furthermore, we chose several EZH2 or LSD1 potential targets (P15, P21, LATS1, LATS2, RND1, KLF2, E-cadherin, PTEN, ASPP2 and RRAD) with tumor-suppressor function, and hypothesized that they may involve in the contributions of AGAP2-AS1 to NSCLC progression." (PMID 27195672, 2016). "However, unlike in the Fuji xenograft model, EZH2 inhibition did not lead to a decrease in tumor growth, although H3K27Me3 levels were found to be inhibited in tumors collected at study end, and these cells were growth inhibited with tazemetostat in vitro." (PMID 27391784, 2016). "3-deazaadenosine A (DZNep) is a non-specific EZH2 inhibitor which decreases its protein levels and removes the H3K27me3 marks from the chromatin and shows significant anti-tumor effect in various malignancies with reported efficacy but also toxicity in animal models." (PMID 27793053, 2016). "However, deleterious mutations in EZH2 have been found in T-ALL patients (mainly associated with immature and not more differentiated cases), suggestive of a tumor suppressor role in T-cells." (PMID 26882564, 2016). "Despite the extensive research evaluating the role of EZH2 as a promoter of cancer progression through the induction of cell cycle and inhibition of cancer cell differentiation, the effects of EZH2 expression on the tumor immunity have not been fully appreciated." (PMID 27199994, 2016).
tumor (continued). "A recent study demonstrates that mutations in EZH2 affects the tumor suppressor activity of SWI/SNF subunits and it also suggests that inhibitors of EZH2 in developmental phase will also not fully control the oncogenic activity of EZH2." (PMID 27250031, 2016). "The exact role of EZH2 in bypassing senescence is as yet not clear and may depend on tumor cell type." (PMID 25853770, 2015). "In this context, we have recently shown that EZH2 mediates recurrence in NMIBC, being also upregulated in tumor samples and especially in recurrent tumors.The current study gives an insight into the regulation of HOTAIR, indicating that EZH2 may regulate HOTAIR expression." (PMID 26457124, 2015). "In addition, the roles of EZH2 do not seem to be limited to miR-200 expression, as other various miRNAs with potential oncogenic (miR-221, miR-222) or tumor suppressor (miR-30a, miR-145) activity in bladder also appear to be modulated by EZH2." (PMID 26517683, 2015). "Moreover, there is evidence showed that EZH2 could directly bind to KLF2 promoter and silence of KLF2 expression result in blocking the tumor-suppressor features of KLF2, which is partly mediated by p21." (PMID 26336870, 2015). "Although the function of EZH2 is still unclear, recent research revealed that phosphorylation of EZH2 at serine 21 (pS21 EZH2) by AKT facilitates STAT3 methylation by EZH2 and enhances STAT3 activity, which is necessary to maintain GBM stem-like cell self-renewal and tumor malignancy." (PMID 25823657, 2015). "An additional E2F1 target regulated by miR-10b, EZH2, is the catalytic subunit of Polycomb Repressor complex 2, overexpressed in various malignancies, including GBM, that inhibits differentiation, activates cell cycle, increases cell motility, and enhances self-renewal and tumor initiating capacity." (PMID 25738367, 2015). "GSK126 could effectively suppress proliferation of EZH2 mutant DLBCL cell lines and inhibit tumor growth in xenograft mouse model of EZH2 mutant DLBCL in vivo, indicating pharmacological inhibition of EZH2 activity may show promise in treating DLBCL harboring activating mutations of EZH2." (PMID 25520914, 2014). "Phosphatase and tensin homolog deleted from chromosome 10 (PTEN) is a lipid phosphatase that antagonizes the action of phosphatidylinositol-3 kinase (PI3K), and thereby acts as tumor suppressor gene, and the relation between EZH2 and PTEN has not been unclear now." (PMID 25084021, 2014). "In this study, we report that, as for transcripts, EZH2 protein is aberrantly over-expressed in 19 out of 19 embryonal RMS primary tumors compared to normal muscle tissues, thus indicating that the high level of expression of EZH2 is a common molecular lesion of embryonal RMS neoplasia." (PMID 24575771, 2014). "However, the role of EZH2 in other steps of the metastatic process, such as tumor angiogenesis, has never been documented in NPC." (PMID 25237831, 2014). "Of note, the suppression of EZH2 by shRNA and pharmacologically by 3-deazaneplanocin A was sufficient to reduce both H3K27me3 and sphere formation, opening avenues for the use of EZH2 inhibitors to reverse EMT-induced tumor resistance to hypoxia or chemotherapeutics." (PMID 24367927, 2013). "The results obtained from eleven tumor specimens from this phase II clinical trial are exciting because it showed, for the first time, that let-7 miRNAs could be upregulated in tumors by BR-DIM intervention with consequent down-regulation of EZH2." (PMID 22442719, 2012). "As far as we know EZH2 expression has not previously been examined in this type of tumor." (PMID 22809481, 2012). "To corroborate the role of EZH2 and CTNNB1 in miR-214-mediated tumor cell invasion, we rescued the expression of EZH2 and CTNNB1 in miR-214 stable transfected HLE cells by transfecting a plasmid carrying wild-type EZH2 (pLVTHM-EZH2) or CTNNB1 (pCI-CTNNB1, Addgene)." (PMID 22962603, 2012).
tumor (continued). "Moreover, the expression of miR-98 (or miR-214) was inversely correlated with EZH2 protein but not mRNA expression in tumor tissues." (PMID 22867052, 2012). "Furthermore, scores of EZH2 and H3K27me3, but not of Ki-67, were significantly higher in patients with larger tumor size, and all three markers were significantly higher in those with distant metastasis." (PMID 23110793, 2012). "In multivariate Cox proportional analyses with disease stage as the co-factor, EZH2 expression in tumor tissue relative to matched adjacent normal lung tissue was the independent predictors of disease-free survival (hazard ratio = 0.045, 95% CI: 0.270 to 0.750, P = 0.002)." (PMID 23300840, 2012). "We also observed relatively strong EZH2 expression in tumor adjacent nonmalignant lung tissue, which may result from the chronic carcinogen exposure of the entire lung." (PMID 23300840, 2012). "EZH2 was detected in all the tumor cell lines (including Jurkat), but not in PBMCs." (PMID 22053850, 2011). "To analyse whether such allo-restricted cytotoxic T cells can inhibit tumour growth in vivo, we challenged Rag2−/−γC−/− mice s.c. intra-inguinally with EWS-FLI1+ HLA-A*0201+ A673 ET cells, followed by i.v. injection of EZH2 (n=7) or CHM1 (n=6) specific T cells 3 days later." (PMID 21407224, 2011). "This indicates that detectable EZH2 expression is not stringently restricted to tumor cells." (PMID 20920340, 2010). "For analyzing RCC patients without metastases, our Cox regression model-which included tumor stage, grading, Karnofsky performance index, age, sex, histopathological subtype, and EZH2 expression-revealed a concordance probability of 73.4% compared to 71.8% excluding EZH2 expression." (PMID 20920340, 2010). "Indeed, reconstitution of Ezh2, but not its inactive methyltransferase mutant either by F667I mutation, or by deletion of the catalytic SET domain, fully reversed MHC-I expression levels in Usp22-null tumor cells." (PMID 41252204, 2025). "GSK343, a novel EZH2 inhibitor, has been shown to regulate apoptosis and autophagy by modulating canonical and non-canonical NF-κB/IκBα pathways and may demonstrate efficacy in inhibiting GBM cell proliferation in vitro and tumor growth in subcutaneously transplanted tumor mouse models." (PMID 40450300, 2025). "Therefore, further exploration is needed to determine whether EZH2 can similarly affect tumor immunity through PD‐L2 modulation (data not shown)." (PMID 38520088, 2024). "Therefore, these molecules may already be expressed in adenocarcinomas, depending on the tumor cell-of-origin and EZH2 inhibition may not be able to boost the expression levels." (PMID 38265267, 2024). "The awareness of the tumor-biological implications of non-canonical EZH2 functions in cancer progression resulted in the development of next-generation EZH2 inhibitors, which degrade the EZH2 protein, and hence are more likely to also target non-canonical EZH2 activities." (PMID 35884510, 2022). "In addition, we found that miR-138 was negative correlation with EZH2 expression in tumor tissues." (PMID 35505294, 2022). "Although studies have shown the promising combination of EZH2 inhibitors and PARP inhibitors in tumor therapy, the combination scheme of EZH2 inhibitors and PARP inhibitors does not always show antitumor effects, which may be related to the tumor immune microenvironment." (PMID 36263120, 2022). "Furthermore, finding the proper combination such as combined with immunotherapies (such as anti-PD1, anti-PD-L1, and anti-CTLA4), targeting drugs, chemotherapies etc. may be the best approach to increase the anti-tumor effectiveness of GSK126 and other EZH2 inhibitors." (PMID 35432300, 2022). "Furthermore, EZH2 functions in restricting glycolysis in T cells within the TME through the glycolytic pathway, which leads to reduced proinflammatory cytokine expression and poor survival of CD8+ T cells, thus ultimately increasing the tumor burden and metastatic potential of the melanoma model." (PMID 34737746, 2021).
tumor (continued). "Although both studies suggest that suppression of EZH2 is a promising therapeutic strategy, additional studies that singularly target EZH2 and not multiple targets are needed to gauge better whether EZH2 suppression alone is a viable strategy to arrest tumor proliferation and disease progression." (PMID 34771443, 2021). "In addition, both studies noted that EZH2 inhibition resulted in positive changes in the CD8+ T cell antitumor immune responses, including an increase in the frequency of IFNγ-producing CD8+ T cells and reduced inhibitory marker expression on tumor-infiltrating T cells." (PMID 33117406, 2020). "Regarding miR-26a, we previously showed that this miRNA is significantly downregulated in PCa tissue samples and could exert tumor-suppressive functions possibly by regulating genes that are upregulated in PCa, such as alpha-methylacyl-CoA racemase (AMACR) and enhancer of zeste homolog 2 (EZH2)." (PMID 32784833, 2020). "In addition, given the EZH2-mediated cellular heterogeneity towards resistance, as demonstrated in this study, upfront co-treatment with EPZ-6438 and anti-HER2 therapy might prevent tumor recurrence and metastasis." (PMID 33208750, 2020). "Despite the lack of a sizable number of EZH2 expressing T lymphocytes, we explored the expression of the costimulatory molecule PD‐1 and its ligand PD‐L1 in order to identify potential treatment window of the host immune system being, as expected, tumor cells always negative." (PMID 28627792, 2017). "Viewed in the context of the results of our earlier studies, these data suggest that the tumor phenotype may be due to the promotion of FGF-2 responsiveness by the Akt3/IWS1 pathway and the induction of EMT and stem cell self-renewal by FGF-2 via the FGF-2/KDM2B/miR-101/EZH2 pathway." (PMID 28515962, 2017). "Interestingly, EZH2 overexpression in NKTL was found not to be associated with H3K27 trimethylation, and ectopic expression of an EZH2 mutant lacking HMTase activity in NKTL cell lines rescued the tumor growth inhibition resulting from depletion of endogenous EZH2." (PMID 28415635, 2017). "Translated to the clinic this would imply that before targeting EZH2 in the context of MPNST it is imperative to verify whether the PRC2 complex is in fact inactivated e.g. by determining the absence of H3K27 trimethylation (H3K27me3) in the tumor tissue." (PMID 28813519, 2017). "However, EZH2 was absent or weakly expressed in the paired non-tumor tissues." (PMID 27706111, 2016). "Since EMT has been critically discussed as the key process in tumor aggressiveness and metastasis, our findings in the present study demonstrate that miR-26a as a suppressive miRNA could inhibit tumor metastasis and invasion partly by impeding EMT through repression of EZH2." (PMID 26733151, 2016). "However, similar to the Hi-Myc model, deletion of Ezh2 did not prevent tumor development (n = 7)." (PMID 26637281, 2015). "Furthermore, increased expression of EZH2 and BMI1 results in additional downregulation of miR-200 members, which leads to the subsequent upregulation of EMT-promoting transcription factors and favors the invasive behavior of the tumor cells and the progression into MIBC." (PMID 26517683, 2015). "Indeed, EZH2 inhibition by siRNAs, or depletion of PRC2 components by the drug 3-deazaneplanocin A (DZNep), exerted antioncogenic effects, by blocking cell proliferation and/or inducing apoptosis, by counteracting invasion and metastasis, and by inhibiting tumor angiogenesis." (PMID 21765901, 2011). "In addition, overexpression of EZH2 in basal-like tumours could methylate non-histone targets potentially adding further differences between basal-like and lumB tumours." (PMID 20565864, 2010). "The concurrent inhibition of EZH2 and DNMT1, but not individual agents, significantly boosts T cell infiltration, slows down tumor progression, and enhances the therapeutic response to the PD-L1 checkpoint blockade in tumor-bearing mice." (PMID 39858465, 2025).